LRP5 (LDL receptor related protein 5)
Diseases named in the same sentence as LRP5 in open-access papers (continued):
Sharing a sentence is not in itself a finding about the gene and the disease.
Insulin resistance (5 papers, 2019 to 2025). Increased resistance towards insulin, that is, diminished effectiveness of insulin in reducing blood glucose levels. "Compared to controls, GoF LRP5 mutation carriers exhibited lower fasting glucose, fasting insulin, Homeostatic Model Assessment for Insulin Resistance (HOMA-IR), HOMA of β-cell function (HOMA-B), and adipose tissue insulin resistance (Adipo-IR)." (PMID 40000740, 2025). "More studies need to be carried out in Iranian and other population groups to understand the correlation between LRP5 polymorphism and insulin resistance to further verify our results." (PMID 30866603, 2019). "This study showed that LRP5 polymorphism (rs556442) was associated with insulin resistance in Iranian children and adolescents." (PMID 30866603, 2019). "Due to the relatively small sample size, statistical power to detect associations of LRP5 variants with insulin resistance was limited." (PMID 30866603, 2019). "In conclusion, this study showed that LRP5 polymorphism (rs556442) was associated with insulin resistance in Iranian children." (PMID 30866603, 2019). "In this study, we evaluated the association of LRP5 (rs566442) polymorphism with insulin resistance indexes HOMA-IR, QUICKI, insulin-to-glucose ratio, McAuley, revised McAuley, FIRI, and Bennett’s index." (PMID 30866603, 2019). "In this study, for the first time, the association of LRP5 (rs556442) polymorphism and insulin resistance in Iranian children and adolescents was investigated." (PMID 30866603, 2019). "Moreover, the lack-of-function of LRP5 causes insulin resistance, which can be reversed using the gain-of-function." (PMID 37569816, 2023). "For this reason, in this paper we investigated whether LRP5 (rs556442) polymorphism is associated with insulin resistance in Iranian children and adolescents." (PMID 30866603, 2019). "Furthermore, the larger sample size would help to elucidate the association of LRP5 with insulin resistance and other metabolic diseases." (PMID 30866603, 2019). "Similarly, insulin resistance has been observed in humans with diminished white adipose tissue LRP5 expression." (PMID 40940800, 2025). "However, the relationship of LRP5 (rs556442) polymorphism with insulin sensitivity and insulin resistance in children has not been examined as yet." (PMID 30866603, 2019). "Mice lacking Lrp5 in mature osteoblasts and osteocytes displayed decreased postnatal bone mass alongside higher fat mass, elevated plasma triglycerides and NEFA on a chow diet, and glucose intolerance and insulin resistance following a HFD51,52." (PMID 40000740, 2025).
retinal diseases (5 papers, 2011 to 2023). "Pathogenic variants in genes that play key roles within this pathway, such as NDP, FZD4, TSPAN12, and LRP5, have been associated with the incidence of these retinal diseases." (PMID 37947657, 2023). "Missense mutations in the coding DNA cause moderate retinal disease when at the LRP5/6 binding sites and severe retinal disease when at the FZD4 binding sites or when a cysteine is lost." (PMID 35651932, 2022). "The pathway co-receptor, low density lipoprotein receptor-related protein 5 (LRP5), is involved in the pathogenesis of retinal diseases and has been implicated in glaucoma." (PMID 21528003, 2011). "Our results show that there is a clear association between mutations in the FZD4 binding site and ‘severe’ retinal disease (severe in four out of 5 cases) whereas LRP5/6 binding site mutations universally caused moderate disease (moderate in four out of 4 cases)." (PMID 35651932, 2022). "Thus, LRP5 may be an effective and specific target for preventing or treating retinal diseases caused by neovascularization in the photoreceptor cell layer and subretinal space." (PMID 24058663, 2013). "Therefore defective FZD4 function ought to produce ‘severe’ retinal disease whereas defective LRP5 function ought to produce ‘moderate’ disease." (PMID 35651932, 2022).
colorectal cancer (4 papers, 2014 to 2025). A primary or metastatic malignant neoplasm that affects the colon or rectum. "Analysis of expressed mutated surface genes revealed recurrent mutations in genes belonging to pathways known to be involved in colorectal cancer, including the WNT (LRP5 and FZD10), TGFβ (TGFBR3 and ACVR1B) and RTK-Ras (EGFR and ERBB3) signaling pathways." (PMID 25193853, 2014).
diabetic retinopathy (4 papers, 2016 to 2025). "SZN-413, a FZD4/LRP5-targeting Norrin mimetic molecule, is an essential therapeutic option for diabetic retinopathy." (PMID 40940800, 2025). "Thus, an endothelial autonomous function of LRP5 is a key component of the cellular mechanisms underlying OPPG and likely diabetic retinopathy as well." (PMID 27031698, 2016). "FZD4/LRP5 agonists also reduce neovascular tufts in mice with oxygen-induced retinopathy; therefore, this class of agonists appears to target multiple processes relevant to diabetic retinopathy, including promoting BRB function and reducing pathological neovascularization." (PMID 41086024, 2025). "Similarly, F4L5.13, a tetravalent diabody with a dumbbell-like structure, has also been found to demonstrate comparable results in the treatment of diabetic retinopathy by acting against FZD4 and LRP5 receptors and LRP5 signaling." (PMID 40940800, 2025).
dyslipidemia (4 papers, 2012 to 2025). "Mutations in Lrp5/6 are associated with bone disorders, abnormal ocular vascularization, early onset cardiovascular disease and metabolic syndrome." (PMID 22438981, 2012). "The LRP5 gene codes for low-density lipoprotein receptor-related protein 5, and differential methylation of CpG sites within this gene have previously been associated with passive smoking exposure, and implicated in the proposed link between cigarette smoking habit and metabolic syndrome." (PMID 39277688, 2025).
glioma (4 papers, 2012 to 2025). A benign or malignant brain and spinal cord tumor that arises from glial cells (astrocytes, oligodendrocytes, ependymal cells). "A series of experiments such as cell proliferation assay, flow cytometry analysis, and Western blotting were used to determine the role of LRP5 in glioma cell proliferation, cell cycle progression, and the underlying mechanisms." (PMID 39991761, 2025). "The objective of this study is to explore the influence of LRP5 in glioma cell proliferation and its potential molecular mechanisms." (PMID 39991761, 2025). "When differentiating between normal individuals and glioma patients, the area under the receiver operating characteristic curve (ROC) for LRP5 was determined to be 0.981." (PMID 39991761, 2025). "Downregulating the expression of LRP5 in glioma cells can weaken their proliferative ability and reduce the number of cell colonies." (PMID 39991761, 2025). "Glioma cell lines with reduced LRP5 expression were established through RNA interference." (PMID 39991761, 2025). "However, the function of LRP5 in glioma has not been elucidated." (PMID 39991761, 2025).
hyperostosis (4 papers, 2019 to 2025). Excessive thickening of bone. "Here, we present the case of a young female patient diagnosed with a heterozygous variant of the LRP5 gene (c.844A>G, p.Met282Val) leading to hyperostosis to explore possible complications and treatment options for this disease." (PMID 40585686, 2025). "LRP5 high bone mass (HBM) is an autosomal dominant endosteal hyperostosis caused by mutations of the low-density lipoprotein receptor-related protein 5 (LRP5) gene." (PMID 37659026, 2023). "When a case of hyperostosis is suspected, genetic analysis leading to the appropriate diagnosis of LRP5 HBM is fundamental to continue to better our understanding of this disease." (PMID 40585686, 2025). "Conversely, patients with LRP5 G171V, a gain-of-function mutant of LRP5, exhibited hyperostosis (OMIM: 144750)." (PMID 31698687, 2019). "We present the only historical review on Worth-type endosteal hyperostosis, now known as LRP5 HBM." (PMID 37659026, 2023). "Substitution of glycine with valine at codon 171 of LRP5 changes BP1 domain conformation, leading to decreased affinity towards sclerostin and DKK1, followed by the development of hyperostosis by triggering the canonical Wnt signaling pathway." (PMID 31698687, 2019).
Impaired glucose tolerance (4 papers, 2014 to 2025). An abnormal resistance to glucose, i.e., a reduction in the ability to maintain glucose levels in the blood stream within normal limits following oral or intravenous administration of glucose. "Impaired glucose tolerance, as well as high glucose concentrations were found, demonstrating the importance of LRP5 in this signaling." (PMID 30304114, 2018).
myocardial ischemia (4 papers, 2019 to 2025). A disorder of cardiac function caused by insufficient blood flow to the muscle tissue of the heart. "While β-catenin exacerbates ischemic injury, the integral basal signaling of LRP5/6 is crucial for protecting against myocardial ischemia damage." (PMID 39482911, 2025). "We also demonstrated the functional importance of LRP5-transported PUFAs in neutrophils; LRP5-transported PUFAs protect mice from myocardial ischemia-reperfusion injury." (PMID 38594269, 2024). "Interestingly, although Dkk1 inhibits the overexpression of nuclear β-catenin and downregulates LRP5/6, its overall effect appears to enhance myocardial ischemia injury through further downregulation of LRP5/6." (PMID 39482911, 2025). "Thus, we tested and found that Mrp8-Cre-driven LRP5 (Lrp5N) KO mice also had increased myocardial ischemia-reperfusion injury and elevated neutrophil NET formation." (PMID 38594269, 2024). "Thus, the increased mTORC1 signaling and NET formation likely exacerbated myocardial ischemia-reperfusion injury in the neutrophil-specific LRP5 KO mice." (PMID 38594269, 2024). "Thus, we investigated the roles of myeloid LRP5 and 6 in modulating injury during myocardial ischemia-reperfusion, a condition in which neutrophils play an important role." (PMID 38594269, 2024). "To determine if LRP5-transported PUFAs play an important role in neutrophil function in vivo, we examined the effects of PUFA-deprivation on myocardial ischemia-reperfusion injury." (PMID 38594269, 2024). "In contrast to the previous findings in mice on a normal diet, the essential fatty acid-free diet abrogated the differences in myocardial ischemia-reperfusion injury and NET formation between the neutrophil-specific LRP5 KO and control WT mice." (PMID 38594269, 2024). "In addition, injection of DKK2, an antagonist of Wnt signaling, binding to LRP5 and LRP6, was shown to be beneficial for infarct healing in a cardiac ischemia/reperfusion model." (PMID 34205318, 2021). "Therefore, although the modulation of upstream signals of GSK3β in myocardial-ischemia has been investigated previously, myocardial ischemia models were different, and none of these studies inhibited LRP5 directly." (PMID 31220102, 2019).
coronary artery disease (3 papers, 2020 to 2025). "This study investigated the relationship between the LRP5 rs556442 gene polymorphism and the risks of non-alcoholic fatty liver disease (NAFLD) and coronary heart disease (CHD) in a Chinese Han population." (PMID 35733105, 2022). "This study explored the relationship between the LRP5 rs556442 gene polymorphism and the risks of non-alcoholic fatty liver disease (NAFLD) and coronary heart disease (CHD) in a Chinese Han population." (PMID 35733105, 2022).
craniosynostosis (3 papers, 2022 to 2025). Craniosynostosis is defined as the premature fusion of one or more cranial sutures leading to secondary distortion of skull shape resulting in skull deformities with a variable presentation. "While our functional studies focused on genes uniquely associated with variation in skull BMD, there are plenty of genes implicated in craniosynostosis (e.g., EN1, RUNX2, SOX6, BMP2, JAG1, LRP5, IDUA30,44,47,48) across the whole set of identified BMD loci." (PMID 37402774, 2023).
cystic kidney disease (3 papers, 2020 to 2025). A congenital or acquired kidney disorder characterized by the presence of renal cysts. "In this scenario, our data are quite interesting considering that the clinical picture of our patients correlates with cystic kidney disease, suggesting that the LRP5 gene, in addition to polycystic liver disease, could potentially play a role in PKD predisposition." (PMID 37372416, 2023).
fracture (3 papers, 2014 to 2024). "Although the LRP5 locus appears to affect bone size of the skeleton as a whole, genetically determined FNW only influenced risk of FN/hip fracture, suggesting fractures at the latter site are particularly influenced by bone geometry." (PMID 38477772, 2024).
leukemia (3 papers, 2020 to 2024). A malignant (clonal) hematologic disorder, involving hematopoietic stem cells and characterized by the presence of primitive or atypical myeloid or lymphoid cells in the bone marrow and the blood. "In leukemia, JAM3 maintains leukemia-initiating cell function through the LRP5/AKT/β-catenin/CCND1 signaling pathway and is associated with poor prognosis in leukemia." (PMID 38400838, 2024). "JAM3 is highly enriched in leukemia-initiating cells and play an important role in the maintenance of leukemia-initiating cell stemness through LRP5/PDK1/AKT/GSK3β/β-catenin/CCND1 signaling pathways." (PMID 32979257, 2020).
liver cancer (3 papers, 2019 to 2025). An epithelial or non-epithelial malignant neoplasm that arises from the liver. "Our study implicates LRP5 as a promising therapeutic target for inhibiting liver cancer cell proliferation." (PMID 31881970, 2019). "Knockdown of LRP5 with three distinct siRNAs (siLRP5–1#, siLRP5–2#, and siLRP5–3#) all significantly inhibited the proliferation of HepG2 cells, as well as a separate liver cancer cell line Huh7 cells, indicating that knockdown of LRP5 may generally affect the proliferation of liver cancer cells." (PMID 31881970, 2019). "Here, we examined the effect of LRP5, LRP6, or β-catenin knockdown on liver cancer HepG2 cell proliferation." (PMID 31881970, 2019). "In contrast, LRP5 deficiency results in the destabilization of NUP37, and may lead to the destruction of the NPC integrity, which in turn causes dysregulation in the nuclear translocation of numerous signaling proteins, including those critically involved in the proliferation of liver cancer cells." (PMID 31881970, 2019). "We performed siRNA knockdown of LRP5, LRP6, or β-catenin in liver cancer HepG2 cells to determine the effect on tumor cell proliferation." (PMID 31881970, 2019). "LRP5 therefore acts as a genuine regulator of YAP/TEAD signaling via maintaining the integrity of the NPC, and implicates a therapeutic strategy in targeting LRP5 for inhibiting liver cancer cell proliferation." (PMID 31881970, 2019). "Due to the fact that knockdown of NUP37 also significantly inhibited the proliferation of a separate liver cancer cell line Huh7, as well as non liver cancer cell line HEK-293, LRP5 may play a universal role in the modulation of NPC function via specific stabilization of NUP37." (PMID 31881970, 2019). "Indeed, similar to knockdown of LRP5, knockdown of NUP37 significantly inhibited the proliferation of HepG2 cells and Huh7 cells, as well as a non liver cancer cell line HEK-293 cells." (PMID 31881970, 2019). "We demonstrated that knockdown of LRP5, but not LRP6 or β-catenin, markedly inhibited the proliferation of liver cancer HepG2 cells by destabilizing NUP37 and may result in the subsequent destruction of the NPC integrity." (PMID 31881970, 2019). "However, the role of LRP5 and LRP6 in liver cancer has not been fully investigated." (PMID 31881970, 2019).
lung cancer (3 papers, 2015 to 2022). A malignant neoplasm involving the lung. "Subsequently, the critical role of LRP5/6 in lung cancer progression has also been documented." (PMID 35246020, 2022). "The association between lung cancer and 4 target genes (FZD8, LRP5, PIAS1 andRUNX1) has been previously reported.It has been reported that FZD8is highly expressed in A549 cell line and the dysregulation of FZD8 might play key roles in human cancer through activation of beta-catenin-TCF pathway." (PMID 26642205, 2015).
myocardial infarction (3 papers, 2021 to 2025). Gross necrosis of the myocardium, as a result of interruption of the blood supply to the area, as in coronary thrombosis. "In myocardial infarction, targeting LRP5 restores the viability of myocardial cells and promotes healing after hypoxia by modulating the canonical Wnt pathway." (PMID 40940800, 2025). "It has been reported that LRP5 knockout increases the infarct area after myocardial infarction in mice, suggesting a potential protective role of LRP5 in injured myocardium." (PMID 35429093, 2022). "We suggest that the role of LRP5 as a regulator of HIF-1α stability under hypoxic conditions can be exploited as a novel therapeutic strategy targeting LRP5 for the treatment of myocardial infarction." (PMID 34205318, 2021).
parathyroid tumors (3 papers, 2007 to 2022). "The functional data also show that expression of shortened LRP5 is necessary for the abnormal growth of parathyroid tumor cells." (PMID 18044981, 2007).
pulmonary disease (3 papers, 2012 to 2021). "The Wnt-pathway-related gene LRP5 is strongly associated with the progression of pulmonary disease, and also regulates the immune mechanisms in TB." (PMID 34203447, 2021). "Modulation of LRP5 would potentially lead to the development of new therapeutic strategies for aging-associated lung diseases." (PMID 30612120, 2019). "Modulation of LRP5 signaling would be an efficient therapeutic strategy for aging-associated lung diseases." (PMID 30612120, 2019). "Thus, modulation of the LRP5-Ang/Tie2 system is likely to lead to the identification of new therapeutic targets for neonatal pulmonary diseases such as BPD." (PMID 22848540, 2012).
pulmonary fibrosis (3 papers, 2017 to 2021). Chronic progressive interstitial lung disorder characterized by the replacement of the lung tissue by connective tissue, leading to progressive dyspnea, respiratory failure, or right heart failure. "There has been evidence that global loss of low-density lipoprotein receptor-related protein 5 (Lrp5), a Wnt coreceptor, can mitigate pulmonary fibrosis induced by bleomycin." (PMID 33670759, 2021). "A recent study reported that high LRP5 levels in patients were associated with faster progression of idiopathic pulmonary fibrosis (IPF) through activation of Wnt/β-catenin signaling, implicating an important role of LRP5 in Wnt/β-catenin signaling-related pulmonary fibrotic diseases." (PMID 32345960, 2020). "Indeed, a recent study demonstrated that LRP5/β-catenin signaling controlled alveolar macrophage differentiation and inhibited bleomycin-induced murine pulmonary fibrosis." (PMID 28588349, 2017).
Vitreoretinopathy (3 papers, 2022 to 2024). Ocular abnormality characterized by premature degeneration of the vitreous and the retina that may be associated with increased risk of retinal detachment. "Already in early studies on LRP5 and OPPG, and in many studies thereafter, it has been noticed that carriers of heterozygous rare LRP5 variants also have reduced bone mass but usually lack eye manifestations or may have a milder eye phenotype in the form of vitreoretinopathy." (PMID 34236445, 2022).
Arthritis (2 papers, 2020 to 2024). Inflammation of a joint. "The results from in vivo experiments indicated that EZP combined with MTX reduced arthritis severity, alleviated ankle bone damage, increased BALP and decreased TRACP serum levels, and regulated the mRNA expression of Wnt1, LRP5, β-catenin, Runx2, BALP, and BGP in the ankles." (PMID 32218732, 2020).